TUFM (Tu translation elongation factor, mitochondrial)
Description:
GTP hydrolase that promotes the GTP-dependent binding of aminoacyl-tRNA to the A-site of ribosomes during protein biosynthesis. Participates in mitochondrial translation (By similarity). Also plays a role in the regulation of autophagy and innate immunity. Recruits ATG5-ATG12 and NLRX1 at mitochondria and serves as a checkpoint of the RIGI-MAVS pathway. In turn, inhibits RLR-mediated type I interferon while promoting autophagy.
Synonyms: EFTu; EF-TuMT; COXPD4; P43
Tractability: Small molecule: a structure with a bound ligand is known. PROTAC: ubiquitination databases record sites on it; its protein half-life has been measured; a small molecule that binds it is known.
Gene: Protein-coding gene on chromosome 16 (28,842,410 to 28,846,419, reverse strand). Ensembl gene ENSG00000178952.
Subcellular location: Mitochondrion matrix
Subcellular location (Human Protein Atlas): Mitochondria
Pathways (Reactome):
Disease: SARS-CoV-2 modulates autophagy
Metabolism of proteins: Mitochondrial translation elongation
Gene Ontology:
Molecular function: protein binding; RNA binding; translation elongation factor activity; GTP binding; GTPase activity; magnesium ion binding
Biological process: mitochondrial large ribosomal subunit assembly; translational elongation; mitochondrial translation; mitochondrial translational elongation
Cellular component: extracellular exosome; membrane; mitochondrial matrix; mitochondrial nucleoid; mitochondrion; mitochondrial outer membrane
Genetic constraint (gnomAD): Loss-of-function variants: 23 observed, 46.38 expected, observed/expected ratio (o/e) 0.5, 90% interval 0.36 to 0.7. The upper end of that interval is the gene's LOEUF score, 0.7, which puts it in group 2 of 6, group 1 being the genes least tolerant of losing a copy. Missense variants: 490 observed, 637.15 expected, observed/expected ratio (o/e) 0.77, 90% interval 0.71 to 0.83. Synonymous variants: 243 observed, 263.96 expected, observed/expected ratio (o/e) 0.92, 90% interval 0.83 to 1.02.
Gene-disease validity (ClinGen):
ClinGen rates the evidence that TUFM causes each of these diseases.
mitochondrial disease (autosomal recessive): Moderate.
Homologues: Orthologues: chimpanzee TUFM (100% identical), macaque TUFM (98% identical), pig TUFM (95% identical), rat Tufm (93% identical), mouse Tufm (93% identical), dog TUFM (93% identical), guinea pig TUFM (93% identical), rabbit TUFM (76% identical), zebrafish tufm (72% identical), Drosophila melanogaster mEFTu1 (61% identical), Caenorhabditis elegans tufm-1 (52% identical). Paralogues in human: EEF1A2 (29% identical), EEF1A1 (29% identical), GSPT1 (24% identical), GSPT2 (24% identical), GTPBP1 (22% identical), MTIF2 (22% identical), EFL1 (21% identical), HBS1L (21% identical), EIF2S3 (20% identical), EIF2S3B (20% identical), GFM1 (20% identical), EEFSEC (19% identical), and 6 more.
Diseases named in the same sentence as TUFM in open-access papers:
TUFM is named in the same sentence as 68 diseases in open-access papers, as found by Europe PMC text mining. Sharing a sentence is not in itself a finding about the gene and the disease. The quoted sentences say what the papers report.
lactic acidosis (7 papers, 2016 to 2024). Metabolic acidosis characterized by the accumulation of lactate in the body. "Homozygous or compound heterozygous mutations in the TUFM gene cause combined oxidative phosphorylation deficiency 4, characterized by severe early-onset lactic acidosis and progressive fatal infantile encephalopathy." (PMID 39039444, 2024). "TUFM mutation can result in dysfunction of oxidative phosphorylation and lead to lactic acidosis and fatal encephalopathy." (PMID 29854750, 2018). "Mutations in TUFM are shown to contribute to oxidative phosphorylation inefficiency and lactic acidosis in infantile encephalopathy." (PMID 26919708, 2016). "Mutations in TUFM are associated with OXPHOS deficiency, which leads to lactic acidosis and fatal encephalopathy." (PMID 34277617, 2021). "A pathogenic variant in TUFM, located in the domain responsible for TUFM-TSFM interaction, caused lactic acidosis and dilated cardiomyopathy without encephalopathy." (PMID 38779771, 2024).
Encephalopathy (5 papers, 2016 to 2024). Encephalopathy is a term that means brain disease, damage, or malfunction. "Interestingly, in other cases of TUFM mutations, encephalopathy was the primary phenotype, and so investigation of the expression ratio of elongation factors in the brain would be valuable, to examine if the expression pattern is similar to that of the heart." (PMID 38779771, 2024). "Therefore, TUFM may affect the function of the mitochondrial respiratory chain by regulating mitochondrial translation and may play an important role in encephalopathy and other diseases." (PMID 34277617, 2021).
Obesity (5 papers, 2015 to 2025). Accumulation of substantial excess body fat. "The Chr16p11 gene set consists of 212 genes, some of which are associated with obesity, including SH2B1, APOBR, SULT1A1, SULT1A2, and TUFM." (PMID 29854750, 2018).
viral infection (5 papers, 2017 to 2024). "Three host proteins associated with viral infections, vimentin (VIM), tripartite motif-containing protein 21 (TRIM21), and Tu translation elongation factor (TUFM) interacted with D1133L in vitro." (PMID 36406406, 2022). "For example, TUFM is known to mediate autophagy by interacting with the mitochondrial protein NLRX1 upon virus infection." (PMID 34511600, 2022). "Overall, our findings further understanding of the role of TUFM in connecting autophagy and apoptosis and have broader therapeutic implications with respect to virus infections and cancer." (PMID 34511600, 2022). "Moreover, three randomly selected proteins associated with viral infections: VIM, TRIM21, and TUFM were confirmed to interact with D1133L by co-IP and IFA assays." (PMID 36406406, 2022). "No significant localization differences were observed between PB2627K and PB2627E, and TUFM signals were detected in mitochondria regardless of whether or not there was viral infection." (PMID 28611246, 2017).
colorectal cancer (4 papers, 2017 to 2024). A primary or metastatic malignant neoplasm that affects the colon or rectum. "TUFM collaborates with ubiquitin-specific peptidase five to regulate the growth of colorectal cancer cells and can serve as a new prognostic indicator for colorectal carcinoma." (PMID 38213773, 2024). "TUFM is highly expressed in several cancers including glioblastoma, cholangiocarcinoma, and colorectal cancer (CRC), and increased expression of TUFM is associated with shorter patient survival in CRC." (PMID 34511600, 2022). "We therefore presume that colorectal adenoma-to-carcinoma transformation may start in cells that already express TUFM and that TUFM may play important roles in the carcinogenesis and progression of colorectal cancer." (PMID 28449687, 2017). "A previous study demonstrated that mitochondrial Tu translation elongation factor (TUFM) might serve as an independent prognostic factor for colorectal cancer." (PMID 28449687, 2017). "On the other side, TUFM overexpression was reported negative prognostic factor for colorectal cancer and human pancreatic adenocarcinoma." (PMID 29707108, 2018).
lung carcinoma (4 papers, 2017 to 2025). "TUFM downregulation can induce metastasis and proliferation of lung cancer cells via the AMP-activated protein kinase signalling pathway." (PMID 38213773, 2024). "Indeed, in the case of TUFM, a direct association between its down-regulation and induction of EMT and carcinogenesis was shown for lung cancer, and its down-regulation as an indicator of an advanced stage of disease was shown for gastric cancer." (PMID 29707108, 2018). "In lung cancer cells, the downregulation of the TU translation elongation factor mitochondrial (TUFM), a key factor in the translational expression of mitochondrial DNA, is associated to the maintenance of the mesenchymal phenotype of cancer cells and to the acquisition of more aggressive features." (PMID 28352611, 2017). "Downregulation of TUFM promotes epithelial-mesenchymal transition (EMT) and invasion in lung cancer cells through a mechanism that involves AMPK-GSK3β signaling." (PMID 40568577, 2025).
glioblastoma (3 papers, 2018 to 2022). The most malignant astrocytic tumor (WHO grade IV). "Here, we present evidence for TUFM overexpression in GBM and glioblastoma stem cells." (PMID 29707108, 2018). "Western blotting was employed to validate the expression of TUFM protein in normal brain tissue, GBM tissue, neural stem cells (NSCs), GSCs, and U251MG and U87MG GBM glioblastoma cell lines." (PMID 29707108, 2018).
Alzheimer disease (2 papers, 2024). A progressive, neurodegenerative disease characterized by loss of function and death of nerve cells in several areas of the brain leading to loss of cognitive function such as memory and language. "TUFM has been implicated in Alzheimer’s disease (AD) pathology by regulating BACE1 translation, apoptosis, and Tau phosphorylation." (PMID 39478699, 2024). "In recent years, TUFM has been identified as playing significant roles in mitophagy and autophagy and is associated with diseases such as non-alcoholic fatty liver disease, Alzheimer’s disease, and multiple sclerosis." (PMID 39280009, 2024).
breast carcinoma (2 papers, 2023 to 2025). "Among them, TR57 inhibits the growth and proliferation of SUM159 tumor cells of breast cancer by inducing ISR and endoplasmic reticulum stress response marker ATF4 and CHOP protein expression levels, inhibiting TFAM and TuFM protein expression levels, and inhibiting colony formation ability." (PMID 40395852, 2025). "Further, in human breast cancer SUM159 cells, D9 activates ClpP, promoting the degradation of mitochondrial transcription factor A (TFAM) and mitochondrial Tu translation elongation factor (TuFM)." (PMID 40395852, 2025).
glioma (2 papers, 2018 to 2022). A benign or malignant brain and spinal cord tumor that arises from glial cells (astrocytes, oligodendrocytes, ependymal cells). "TUFM was recognized among seven possible glioma tumor-class predictive biomarker candidates in our previous study." (PMID 29707108, 2018).
melanoma (2 papers, 2024). A malignant, usually aggressive tumor composed of atypical, neoplastic melanocytes. "2D proteomic analysis also identified a differential representation of NDUFS1 (core component of ETC Complex I) and TUFM (mitochondrial translation regulator) proteoforms, suggesting mTORC2 regulation on mitochondrial dynamics in melanoma." (PMID 38755661, 2024). "These include a previously undocumented exon of gene TUFM (AltAnalyze: I8.1_28843525-E9.1) that is highly specific to melanoma patients (BayesTS score = 0.029), whereas an exon-skipping event DPM1 (E6.1–E8.2) is broadly present in healthy tissues (BayesTS score = 0.864)." (PMID 39515334, 2024). "Interestingly, spots identified in both M14 and A375 RICTOR-deficient cells contained TUFM, a key regulator of mitochondrial protein translation and oxidative phosphorylation, processes previously implicated in adaptive resistance to BRAFi in BRAFV600E melanoma cells." (PMID 38755661, 2024).
adenoma (1 paper, 2017). A neoplasm arising from the epithelium. "This association indicated that upregulated TUFM expression during the colorectal normal–adenoma–carcinoma sequence may contribute to the transformation from normal mucosa to carcinoma through adenoma." (PMID 28449687, 2017). "With respect to the grade of the adenoma, the positive rate of TUFM expression in adenomas with severe dysplasia was much higher than that in adenomas with mild and moderate dysplasia (P = 0.001)." (PMID 28449687, 2017). "Expression of TUFM protein was found primarily in the membrane and cytoplasm of adenoma or carcinoma cells." (PMID 28449687, 2017). "TUFM protein was scored as positive in 22.2% (58/261) of normal mucosa, 42.0% (66/157) of adenoma, and 72.1% (75/104) of carcinoma tissues." (PMID 28449687, 2017). "The positive rate of TUFM expression in adenomas with severe dysplasia or with cancer transformation was much higher than that in adenomas with mild-grade dysplasia." (PMID 28449687, 2017). "In conclusion, upregulated TUFM expression may play an important role in the transformation from colorectal normal mucosa to carcinoma through adenoma." (PMID 28449687, 2017). "Upregulated TUFM expression may play an important role in the transformation from colorectal normal mucosa to carcinoma through adenoma." (PMID 28449687, 2017). "We proposed that TUFM might play a role in the colorectal normal–adenoma–cancer sequence." (PMID 28449687, 2017). "Therefore, TUFM-positive cells may promote the transition from adenoma to carcinoma." (PMID 28449687, 2017). "However, the expression and function of TUFM in the normal–adenoma–cancer sequence have not been reported." (PMID 28449687, 2017).
autism spectrum disorder (1 paper, 2022). A spectrum of developmental disorders that includes autism, and Asperger syndrome. "Similarly, microduplication of 16p11.2 comprising ATXN2L, TUFM, SH2B1, and ATP2A1 genes can lead to the onset of microcephaly and autism spectrum disorder." (PMID 35722491, 2022).
cervical cancer (1 paper, 2022). A primary or metastatic malignant neoplasm involving the cervix. "The negation of mdivi-1 activation of CASP8 by TUFM depletion and the efficacy of TUFM depletion alone on CASP8 activation in the context of these cervical cancer cells provides further evidence that TUFM functions to promote mitophagy and prevent the accumulation of damaged mitochondria." (PMID 34511600, 2022).
colon tumor (1 paper, 2017). "Our results also showed that TUFM plays an important role in colon tumor progression." (PMID 28449687, 2017).
colorectal adenoma (1 paper, 2017). An adenoma that arises from the colon or rectum. "This indicated that TUFM expression was more frequent in subjects likely to develop colorectal adenoma or carcinoma." (PMID 28449687, 2017). "Selective inhibition of TUFM in tumor cells might lead to mitochondrial collapse; therefore, anti-TUFM antibody-drug conjugates may warrant further evaluation for their ability to destroy TUFM+ cells of colorectal adenoma with canceration and early cancer." (PMID 28449687, 2017). "However, no investigation of TUFM expression and function has been performed in colorectal adenoma." (PMID 28449687, 2017).
Darier disease (1 paper, 2017). Darier disease (DD) is a keratinization disorder characterized by the development of keratotic papules in seborrheic areas and specific nail anomalies. "The genes disturbed by the CNVs mainly involve the SH2B1, TUFM, ATP2A1, and ATP2A2 genes, of which mutations of the single ATP2A2 gene in Darier disease have been found to be connected to the neuropsychiatric abnormalities frequently observed in Darier disease." (PMID 28680393, 2017).
hypogonadism (1 paper, 2025). A disorder characterized by decreased function of the gonads. "NYNRIN, TUFM, and SH2B1 were uniquely identified by colocalization analysis of hypogonadism, while NF1, PABPC4, and SHROOM3 were uniquely identified through colocalization analysis of total testosterone." (PMID 40316537, 2025).
ischemia (1 paper, 2025). A hypoperfusion of the BLOOD through an organ or tissue caused by a PATHOLOGIC CONSTRICTION or obstruction of its BLOOD VESSELS, or an absence of BLOOD CIRCULATION. "Concomitantly, RAB7-TUFM colocalization in mitochondria and lysosomes decreased over time post-OGD, suggesting TUFM recruits RAB7 to damaged mitochondria early in ischemia to initiate clearance." (PMID 40585970, 2025).
metabolic syndrome (1 paper, 2021). A cluster of metabolic risk factors for CARDIOVASCULAR DISEASES and TYPE 2 DIABETES MELLITUS. "In addition, these results also provide an insight into the potential role of TUFM in treating metabolic syndrome." (PMID 33398033, 2021).
monoclonal gammopathies (1 paper, 2021). "To elucidate whether the increase in mtDNACN was correlated with the expression of mitochondrial biogenesis regulators, we measured the levels of TUFM and TFAM by quantitative PCR in the different states of monoclonal gammopathies." (PMID 34202390, 2021).
morbid obesity (1 paper, 2021). An excess of body weight, normally defined as an individual with a body mass index greater than 35 or a body weight greater than one hundred percent of ideal body weight. "2, TUFM, SH2B1, ATP2A1-AS1, and RABEP2) located in the 16p11.2 region, SH2B1 was reported as the causal gene of morbid obesity." (PMID 34529725, 2021).
muscle atrophy (1 paper, 2022). The loss of muscle tissue due to inactivity or disease. "Resistive Exercise (RE) with superimposed vibration mechanosignals (RVE) is proposed to counter muscle atrophy, which is effective against the over expression of Mitochondrial Ribosomal Proteins (MRPs) and Mitochondrial Tu Translation Elongation Factor (TUFM) that cause muscle atrophy." (PMID 35328027, 2022).
myocardial ischemia (1 paper, 2025). A disorder of cardiac function caused by insufficient blood flow to the muscle tissue of the heart. "RAB7 conferred protection against myocardial ischemia by facilitating TUFM recruitment to the damaged mitochondria and promoting mitophagy." (PMID 40585970, 2025).
neuroblastoma (1 paper, 2010). Neuroblastoma (NB) is the most common solid, extracranial childhood tumor. "Products of other genes, i.e., RHOC, RHOA, CCT5 and TUFM, were reported as also being involved in cytoskeleton rearrangements that are necessary for changes of cell morphology during the neuronal differentiation of neuroblastoma cells." (PMID 20459794, 2010).
neuropathy (1 paper, 2024). A disorder affecting the nervous system that manifests with pain, tingling, numbness, and/or muscle weakness. "In the tibial nerve, increased expression of DCXR, GCDH, and TUFM was identified as risk factors for T2DM neuropathy." (PMID 39280009, 2024).
oral cancer (1 paper, 2021). "Similarly, 24 and 72 h POMx treatment inhibits mRNA and protein expressions for mitochondrial biogenesis of gene expression (TFB2M, TFAM, POLRMT, and TUFM) in oral cancer cells." (PMID 34356350, 2021).